ERBB2 (erb-b2 receptor tyrosine kinase 2)
Description:
Protein tyrosine kinase that is part of several cell surface receptor complexes, but that apparently needs a coreceptor for ligand binding. Essential component of a neuregulin-receptor complex, although neuregulins do not interact with it alone. GP30 is a potential ligand for this receptor. Regulates outgrowth and stabilization of peripheral microtubules (MTs). Upon ERBB2 activation, the MEMO1-RHOA-DIAPH1 signaling pathway elicits the phosphorylation and thus the inhibition of GSK3B at cell membrane. This prevents the phosphorylation of APC and CLASP2, allowing its association with the cell membrane. In turn, membrane-bound APC allows the localization of MACF1 to the cell membrane, which is required for microtubule capture and stabilization. In the nucleus is involved in transcriptional regulation. Associates with the 5'-TCAAATTC-3' sequence in the PTGS2/COX-2 promoter and activates its transcription. Implicated in transcriptional activation of CDKN1A; the function involves STAT3 and SRC. Involved in the transcription of rRNA genes by RNA Pol I and enhances protein synthesis and cell growth.
Synonyms: MLN 19; CD340; HER2; NEU; NGL; HER-2; c-ERB2; c-ERB-2; MLN-19; p185(erbB2); HER-2/neu; TKR1; VSCN2
Tractability: Small molecule: an approved drug acts on it; a structure with a bound ligand is known; a high-quality ligand is known; it has a high-quality binding pocket; it belongs to a druggable protein family. Antibody: an approved drug acts on it; UniProt places it where antibodies can reach, with high confidence; its Gene Ontology location is reachable by antibodies, with high confidence; UniProt predicts a signal peptide or a membrane-spanning region; the Human Protein Atlas places it where antibodies can reach. PROTAC: it is named in the literature on targeted protein degradation; ubiquitination databases record sites on it; its protein half-life has been measured; a small molecule that binds it is known. Other modalities: an approved drug acts on it.
Target class: Kinase; Protein Kinase; Tyrosine protein kinase EGFR family; Enzyme; TK protein kinase group
Chemical probes: AFATINIB (high quality), CANERTINIB (high quality), CHEMBL375671, CP-724714 (high quality), LAPATINIB (high quality), PD080811, PD080835, PD081069, PD082259, PD082363, PD082951, PD083163, PD083256, PD083887, PD084042, PD084688, PD085020, SJF1528 (high quality)
Safety:
Unwanted effects reported when the protein is acted on. In parentheses: how it was acted on, where the effect was seen, and who reports it.
cardiotoxicity (source: ClinPGx)
heart disease (cardiovascular system; source: Force et al. (2011))
more sensitive to trastuzamab (source: ClinPGx)
Gene: Protein-coding gene on chromosome 17 (39,687,914 to 39,730,426, forward strand). Ensembl gene ENSG00000141736.
Subcellular location: Cell membrane; Cell projection, ruffle membrane; Cell membrane (Isoform 1); Early endosome; Cytoplasm, perinuclear region; Nucleus; Cytoplasm (Isoform 2); Cytoplasm (Isoform 3)
Subcellular location (Human Protein Atlas): Plasma membrane; Cytosol; Nucleoplasm
Pathways (Reactome):
Disease: Constitutive Signaling by Aberrant PI3K in Cancer; Constitutive Signaling by Overexpressed ERBB2; Drug resistance in ERBB2 TMD/JMD mutants; Resistance of ERBB2 KD mutants to AEE788; Resistance of ERBB2 KD mutants to afatinib; Resistance of ERBB2 KD mutants to lapatinib; Resistance of ERBB2 KD mutants to neratinib; Resistance of ERBB2 KD mutants to osimertinib; Resistance of ERBB2 KD mutants to sapitinib; Resistance of ERBB2 KD mutants to tesevatinib; Resistance of ERBB2 KD mutants to trastuzumab; Signaling by ERBB2 ECD mutants; Signaling by ERBB2 KD Mutants; Signaling by ERBB2 TMD/JMD mutants
Signal Transduction: Downregulation of ERBB2 signaling; Downregulation of ERBB2:ERBB3 signaling; Drug-mediated inhibition of ERBB2 signaling; ERBB2 Activates PTK6 Signaling; ERBB2 Regulates Cell Motility; GRB2 events in ERBB2 signaling; GRB7 events in ERBB2 signaling; PI3K events in ERBB2 signaling; PI5P, PP2A and IER3 Regulate PI3K/AKT Signaling; PIP3 activates AKT signaling; PLCG1 events in ERBB2 signaling; RAF/MAP kinase cascade; SHC1 events in ERBB2 signaling; Signaling by ERBB2
Developmental Biology: Developmental Lineage of Mammary Gland Luminal Epithelial Cells; Developmental Lineage of Mammary Gland Myoepithelial Cells; Developmental Lineage of Mammary Stem Cells; Sema4D induced cell migration and growth-cone collapse
Gene expression (Transcription): TFAP2 (AP-2) family regulates transcription of growth factors and their receptors
Gene Ontology:
Molecular function: ErbB-3 class receptor binding; growth factor binding; identical protein binding; protein binding; protein heterodimerization activity; protein tyrosine kinase activity; receptor tyrosine kinase binding; RNA polymerase I core binding; signaling receptor binding; transmembrane receptor protein tyrosine kinase activity; transmembrane signaling receptor activity; coreceptor activity; ATP binding; protein kinase activity
Biological process: cell population proliferation; cell surface receptor protein tyrosine kinase signaling pathway; cell surface receptor signaling pathway; cellular response to epidermal growth factor stimulus; cellular response to growth factor stimulus; ERBB2-EGFR signaling pathway; intracellular signal transduction; peptidyl-tyrosine phosphorylation; phosphatidylinositol 3-kinase/protein kinase B signal transduction; positive regulation of cell adhesion; positive regulation of cell growth; positive regulation of epithelial cell proliferation; positive regulation of MAP kinase activity; positive regulation of protein targeting to membrane; positive regulation of transcription by RNA polymerase I; positive regulation of translation; regulation of ERK1 and ERK2 cascade; regulation of microtubule-based process; signal transduction; wound healing; enzyme-linked receptor protein signaling pathway; epidermal growth factor receptor signaling pathway; negative regulation of apoptotic process; neuron differentiation; positive regulation of MAPK cascade; and 12 more
Cellular component: basolateral plasma membrane; cytosol; early endosome; endosome membrane; ERBB3:ERBB2 complex; nucleoplasm; nucleus; plasma membrane; receptor complex; basal plasma membrane; membrane; semaphorin receptor complex; apical plasma membrane; cytoplasm; cytoplasmic vesicle; myelin sheath; neuromuscular junction; perinuclear region of cytoplasm; postsynaptic membrane; presynaptic membrane; ruffle membrane
Genetic constraint (gnomAD): Loss-of-function variants: 60 observed, 143.5 expected, observed/expected ratio (o/e) 0.42, 90% interval 0.34 to 0.52. The upper end of that interval is the gene's LOEUF score, 0.52, which puts it in group 2 of 6, group 1 being the genes least tolerant of losing a copy. Missense variants: 1,204 observed, 1,680.8 expected, observed/expected ratio (o/e) 0.72, 90% interval 0.68 to 0.75. Synonymous variants: 633 observed, 684.06 expected, observed/expected ratio (o/e) 0.93, 90% interval 0.87 to 0.99.
Cancer hallmarks: change of cellular energetics (promotes); escaping programmed cell death (promotes); invasion and metastasis (promotes); proliferative signalling (promotes)
Homologues: Orthologues: chimpanzee ERBB2 (99% identical), macaque ERBB2 (97% identical), dog ERBB2 (93% identical), rabbit ERBB2 (93% identical), pig ERBB2 (91% identical), rat Erbb2 (88% identical), mouse Erbb2 (88% identical), guinea pig ERBB2 (87% identical), tropical clawed frog erbb2 (60% identical), zebrafish erbb2 (56% identical). Paralogues in human: EGFR (47% identical), ERBB4 (46% identical), ERBB3 (39% identical), INSR (16% identical), EPHA2 (16% identical), IGF1R (16% identical), EPHA7 (16% identical), EPHA5 (15% identical), EPHB4 (15% identical), INSRR (15% identical), EPHA3 (15% identical), EPHA4 (15% identical), and 41 more.
Diseases named in the same sentence as ERBB2 in open-access papers:
ERBB2 is named in the same sentence as 892 diseases in open-access papers, as found by Europe PMC text mining. Sharing a sentence is not in itself a finding about the gene and the disease. The quoted sentences say what the papers report.
breast cancer (27,302 papers, 1990 to 2026). A primary or metastatic malignant neoplasm involving the breast. "It is located near ERBB2 on chromosome 17 and is frequently co-amplified in HER2-positive breast cancer and this is associated with lower overall patient survival (cBioportal.org)." (PMID 40165206, 2025). "On the other hand, ERBB2 mutations or amplifications have been identified in approximately 15–30% of breast cancers and 10–30% of gastric/gastroesophageal cancers and serve as prognostic and predictive biomarkers for those cancers." (PMID 39985003, 2025). "NSCLC and breast cancer were enriched for KD mutations (69.9% and 77.0% of ERBB2 mutations, respectively), whereas bladder cancer was dominated by ECD mutations (63.6%)." (PMID 40178042, 2025). "For example, breast cancer caused by erbB2 driver gene is classified as a HER2-enriched breast cancer subgroup." (PMID 41294857, 2025). "Some breast cancer cells over-express the ERBB2 gene, which encodes the HER2 protein (HER2-positive breast cancer cells)." (PMID 41153350, 2025). "The key targets involved in breast cancer are estrogen receptor alpha (ERα) and human epidermal growth factor receptor 2 (HER2/neu, encoded by ERBB2)." (PMID 40822245, 2025). "In human breast cancer, the overexpression of ERBB2 has been suggested a strong association with poor prognosis." (PMID 39830364, 2025). "Exon 20 insertions (Ex20Ins) were the dominant mutation type in NSCLC (56.1% of mutations), whereas L755 and V777 were hotspots in breast cancer (a combined 38.4% of ERBB2 mutations)." (PMID 40178042, 2025). "Somatic activating mutations in the ERBB2 (HER2) gene are present in approximately 3–5% of patients with metastatic HR‐positive breast cancer and are associated with endocrine resistance due to crosstalk between HER2 and ER signaling pathways." (PMID 38867388, 2025). "ERBB2 is overexpressed in certain cancers, particularly in breast cancer, and is associated with disease invasiveness and poor prognosis." (PMID 40170854, 2025). "Overexpression of ERBB2, a key driver of cell proliferation and survival, is associated with poor breast cancer outcomes." (PMID 40143209, 2025). "One of these genetic variants, the rs2517956, a 2 Kb upstream variant (G>A) of the ERBB2 gene, was genotyped in 303 breast cancer patients from China, and evaluated according to the HER2 protein expression by IHC." (PMID 40777119, 2025). "Among the 20 patients with pathogenic ERBB2 mutations, only one patient exhibited positive CN amplification [A775_G776insVA (c.2321_2326dup) in breast cancer]." (PMID 40828885, 2025). "In a phase 1 trial for a DNA vaccine encoding HER-2/neu for advanced-stage ERBB2-positive breast cancer (NCT00436254), participants aged 34–77 years were immunized three times with one of three dosages (50, 100, or 500ug)." (PMID 40438110, 2025). "This combination therapy has shown promise in overcoming resistance to anti-ERBB2 monotherapy in HER2+ breast cancer, and ERBB2 has been identified as a key biomarker associated with synergistic responses to this combination in the AZS DREAM Challenge study." (PMID 40459126, 2025). "Exon 20 insertions (including G778_P780dup and Y772_A775dup) in ERBB2 accounted for nearly 15% of all mutations in patients with breast cancer." (PMID 41154672, 2025). "Alpelisib, a selective inhibitor of the p110α subunit of PI3K, has demonstrated substantial clinical efficacy in hormone receptor (HR)-positive, HER2/erbB2-negative breast cancers harboring PIK3CA mutations." (PMID 41347072, 2025). "This updated analysis of the ShortHER randomized clinical trial is, to our knowledge, the first report of a strong independent association of TILs with OS for patients with ERBB2-positive early breast cancer." (PMID 39946142, 2025). "Our findings highlight ERBB2 as a pivotal diagnostic and prognostic biomarker in Egyptian familial breast cancer and support integrating HER2-targeted therapies with immune checkpoint inhibitors and metabolic interventions." (PMID 41403731, 2025).
breast cancer (continued). "In conclusion, the HER2DX ERBB2 mRNA score is significantly associated with improved survival in patients receiving first-line THP for HER2+ advanced breast cancer." (PMID 40280938, 2025). "Cerebrospinal fluid (CSF) tumor-derived DNA (tDNA) analysis by next-generation sequencing (NGS) was ordered, revealing a gain-of-function variant in PIK3CA, ERBB2 copy number gain, and high aneuploidy, findings consistent with breast cancer brain metastasis." (PMID 41149070, 2025). "ERBB2-activating mutations that function as oncogenic drivers have been reported in approximately 4% of breast cancers." (PMID 41154672, 2025). "Overexpression of ERBB2 occurs in approximately 15–30% of breast cancers and is associated with aggressive disease and poor prognosis." (PMID 41472234, 2025). "For instance, in HER2+ (ERBB2+) breast cancer, metformin use was associated with longer IDFS and overall survival, particularly among patients harboring at least one C allele of the rs11212617 single nucleotide variant (SNV)." (PMID 41157306, 2025). "The histological stratification of breast cancers is based primarily on the expression of estrogen receptor (ER), progesterone receptor (PR), and HER2 (also known as ErbB2, encoded by ERBB2)." (PMID 40727661, 2025). "In this cohort study, 55.2% of deaths among patients with ERBB2+ breast cancer and brain metastasis were due to CNS-related causes, with the greatest risk among patients with LMD." (PMID 39888615, 2025). "Though these findings are promising, future research is needed to understand how improved equitable access to ERBB2-targeted therapy is associated with disparities in breast cancer outcomes." (PMID 40310643, 2025). "Human epidermal growth factor receptor 2 (Her2) (alias receptor tyrosine-protein kinase erbB-2 (ERBB2) or cluster of differentiation 340 (CD340))-positive breast cancer patients have high serum levels of CCL5 associated with poor prognosis." (PMID 40076892, 2025). "A 53-year-old female with metastatic estrogen receptor–positive, HER2-negative (IHC 0) breast cancer was found to harbor an ERBB2 V697L mutation identified on tissue NGS." (PMID 40178042, 2025). "Genetic variants or SNPs in ERBB2 have been associated with breast cancer risk, therapy response and resistance to anti-HER2 treatments." (PMID 40777119, 2025). "A previous study has also detailed the impact of ERBB2 specific mutations and activity in breast cancer." (PMID 41154672, 2025). "In the R/M breast cancer cohort, the distribution of mutations in ERBB2, CDK12, and FGFR1 were similar to those in primary breast cancer." (PMID 40182039, 2025). "In contrast, NHE1 is linked to promoting motility in ErbB2-positive breast cancer cells, stimulating the epithelial-to-mesenchymal transition (EMT) and contributing to chemotherapy resistance." (PMID 41515572, 2025). "The study mainly focuses on the ERBB2 gene, which encodes the HER2 protein, and its common mutation HER2-L755S, associated with breast cancer and resistance to the drug lapatinib." (PMID 40177517, 2025). "This was also conducted using a backcross cohort of mice with luminal ERBB2 tumours, as they epitomise an extension of the phenotypic presentation of breast cancer and its associated transcriptomics." (PMID 38344872, 2024). "Aberrant protein expression and mutations in the ERBB2 gene are found in different solid tumors, including breast cancer." (PMID 39402557, 2024). "Mutations in PIK3CA p.E545K and amplification in ERBB2 were common in breast cancers, BRAF p.V600E in metastatic melanoma and IDH1 p.R132H in IDH-mutant gliomas." (PMID 39289779, 2024).
breast cancer (continued). "Human epidermal growth factor receptor-2 (HER2), also known as HER2/erbB2, is a tumor-associated antigen that is over-expressed in ~ 10–20% of breast cancer cases, ~ 3% of cervical and uterine cancer cases, and ~ 27.6% of ovarian cancer cases." (PMID 38722382, 2024). "The ERBB2 (HER2) overexpression is observed in atypical hyperplasia and indicates an increased risk of subsequent breast cancer." (PMID 39684874, 2024). "For example, the PIK3CA H1047R mutation antagonizes lung metastases in a mouse model of ErbB2-induced breast cancer." (PMID 38786098, 2024). "In 2,502 ILBC (5.6% of total breast cancers), ERBB2 amplification is 2.3%, ERBB2 sequence mutation is 9.2%, CDK12 amplification is 0%, and the CDK12 mutation frequency is 0.5%." (PMID 38335502, 2024). "For instance, the presence of ERBB2 (HER2) amplification in breast cancers is associated with more aggressive tumor characteristics and a poorer prognosis." (PMID 39138315, 2024). "This case underscores the potential benefits of neoadjuvant chemoimmunotherapy for patients with ER+ErbB2- high-risk, basal-type breast cancer." (PMID 39006626, 2024). "Among these mutations, ERBB2 is a hotspot mutation in breast cancer that can induce RAS/RAF/MAPK-signaling pathway activity, and the NF1 deletion mutation is also involved in MAPK activation." (PMID 38193944, 2024). "In this context, the different subtypes of ErbB2/neu-positive breast cancers are very aggressive tumors with a high risk of recurrence and poor clinical outcome." (PMID 38892447, 2024). "HK2 knockout can inhibit tumorigenesis in mouse models of KRAS-driven lung cancer, ErbB2-driven breast cancer, and PTEN-deficient PC." (PMID 39770959, 2024). "These reported ERBB2 kinase domain mutations are known to occur in breast cancer and rarely in carcinomas of other organs and are treatable by pan-ERBB2 inhibitors." (PMID 39196362, 2024). "The human epidermal growth factor receptor 2 (HER2; encoded by ERBB2) is overexpressed in ~15–25% of human breast cancers and associates with a poor patient survival." (PMID 38886591, 2024). "The HER receptor family is involved in the regulation of normal breast growth and development, and overexpression of ERBB2/HER2 is associated with breast cancer." (PMID 38638322, 2024). "In conclusion, the presented case highlights the potential efficacy of neoadjuvant chemoimmunotherapy in treating high-risk, basal-type ER+ErbB2- breast cancer, particularly in achieving pathological complete response." (PMID 39006626, 2024). "This is related to the finding that the existence of a mutation in the ERBB2 gene is one of the prognostic indicators of survival for patients with a primary invasive lobular carcinoma subtype of breast cancer." (PMID 38254834, 2024). "For example, ERBB2 (HER2) amplification is observed in up to 30% of breast cancers and is closely associated with poor prognosis and relapse." (PMID 38434478, 2024). "Taking ADCs targeting ERBB2 as an example, in theory, they should be effective against ERBB2 over-expressed/mutated cancers, including breast cancer, gastric cancer, urothelial carcinoma, colorectal cancer, and non-small cell lung cancer." (PMID 39060958, 2024). "ERBB2 mutation is mainly seen in HER2-amplified breast cancers, with an overall incidence of about 3% in all breast cancers." (PMID 39063972, 2024).